DYNC1H1 (dynein cytoplasmic 1 heavy chain 1)
Diseases named in the same sentence as DYNC1H1 in open-access papers (continued):
Sharing a sentence is not in itself a finding about the gene and the disease.
colorectal cancer (4 papers, 2016 to 2023). A primary or metastatic malignant neoplasm that affects the colon or rectum. "Interestingly, Wrn, Abcd4, Ythdc2, and Dync1h1 within this group are noted to have oncogenic function in colon, breast, gastric, and colorectal cancers, respectively." (PMID 36765634, 2023). "DYNC1H1 has been recognized as a driver gene for colorectal cancer to progress to stage‐II." (PMID 34272765, 2021).
Epileptic encephalopathy (4 papers, 2017 to 2025). A condition in which epileptiform abnormalities are believed to contribute to the progressive disturbance in cerebral function. "A de novo mutation of DYNC1H1 associated with epileptic encephalopathy was found to be shared among different neuropsychiatric disorders." (PMID 33374967, 2020).
hereditary spastic paraplegia (4 papers, 2015 to 2022). Hereditary spastic paraplegias (HSP) comprise a genetically and clinically heterogeneous group of neurodegenerative disorders characterized by progressive spasticity and hyperreflexia of the lower limbs. "Other types of neuromuscular diseases, such as hereditary spastic paraplegia (HSP), were also reported to be caused by DYNC1H1 variants." (PMID 35899263, 2022).
autosomal dominant mental retardation 13 (3 papers, 2017 to 2023). "A variant of DYNC1H1, gene associated with Mental Retardation autosomal dominant 13 (MIM 614563), was not retained as causal as this variant has been reported 77 times in the healthy population (gnomAD 2.1.1)." (PMID 31440727, 2019).
developmental delay (3 papers, 2016 to 2023). "We present here a patient with a mutation in the motor domain of DYNC1H1 with a varied clinical presentation including failure to thrive, oral dysphagia, gut dysmotility, congenital cataracts, and developmental delay." (PMID 27754416, 2016). "While the broad findings of developmental delay and polymicrogyria are consistent with previously reported patients with mutations in DYNC1H1, this report suggests other systems can be affected by dynein mutations." (PMID 27754416, 2016).
gastric cancer (3 papers, 2020 to 2022). A primary or metastatic malignant neoplasm involving the stomach. "However, there were no studies clearly illustrated the correlation of these mutation sites of DYNC1H1 with gastric cancer." (PMID 33221769, 2020). "A recent study reported that mutant DYNC1H1 may serve as a biomarker for the therapy of microtubule inhibitors in gastric cancer with high immune activity." (PMID 35739471, 2022). "The reported data showed that DYNC1H1 was overexpressed in gastric cancer cell lines resistant to 5‐fluorouracil, paclitaxel, and cisplatin, suggesting that DYNC1H1 may be used as a biomarker for predicting chemotherapy efficacy in gastric cancer." (PMID 34272765, 2021).
Hyperglycemia (3 papers, 2013 to 2024). An increased concentration of glucose in the blood. "This phenotype is surprising given that mouse fibroblasts derived from Dync1h1+/Cra1 and Dync1h1Cra/Cra1 embryos display profound alterations of mitochondrial morphology and that Dync1h1+/Cra1 mice develop, hyperinsulinemia, hyperglycaemia, and progressive mitochondrial dysfunction." (PMID 24035135, 2013).
infantile spasms (3 papers, 2021 to 2024). A rare epilepsy syndrome characterized by onset of epileptic spasms in infants between 2 and 12 months of age, and rarely up to 24 months. "This study aimed to detect DYNC1H1 variants in Chinese patients with infantile spasms (ISs)." (PMID 34803881, 2021).
pancreatic cancer (3 papers, 2019 to 2022). "DYNC1H1 mutations have been implicated in nervous system diseases and pancreatic cancer, and these mutations are consistent with a high immune activity of tumor mutation load in various cancer types." (PMID 36118697, 2022). "Most mutations of DYNC1H1 were tied up with the occurrence and development of pancreatic cancer, suggesting that mutations in DYNC1H1 may play a vital role in the complex biological process of malignant tumors." (PMID 33221769, 2020). "Inactivating mutations of DYNC1H1 have been found to promote tumorigenesis in pancreatic cancer." (PMID 31249807, 2019).
polymicrogyria (3 papers, 2016 to 2024). A developmental brain abnormality characterized by an excessive amount of small convolutions on the surface of the brain and cognitive dysfunction. "Interestingly, patients with dynein mutations (DYNC1H1) present with a range of developmental phenotypes including polymicrogyria, dysgenesis of the corpus callosum and dysmorphic basal ganglia." (PMID 33137126, 2020).
Sensory neuropathy (3 papers, 2016 to 2024). Peripheral neuropathy affecting the sensory nerves. "A radiation-induced knockout, Sprawling (Swl), contains a 9 bp deletion in the stem domain of Dync1h1 resulting in a dominant phenotype with early onset sensory neuropathy and loss of muscle spindles in hind-limb muscles." (PMID 27754416, 2016). "Notably, a pathogenic variant in DYNC1H1 has been linked to CMT2O, a finding that is supported by mouse models showing that nearby mutations in DYNC1H1 cause a sensory neuropathy phenotype." (PMID 33810506, 2021). "While the role of DYNC1H1 in the enteric nervous system or neural crest cell migration into the gut is unknown, previously reported patients with mutations in DYNC1H1 have exhibited peripheral motor and sensory neuropathies, which may be related to the proband’s phenotype." (PMID 27754416, 2016). "Another mouse model in which muscle spindles fail to form – produced by a deletion in the cytoplasmic dynein heavy chain 1 gene (Dync1h1) – also exhibits an unsteady jerky and wobbling gait and splayed hindlimbs and has a pure proprioceptive sensory neuropathy without any motor involvement." (PMID 37029664, 2024).
amyotrophic lateral sclerosis (2 papers, 2012 to 2023). Amyotrophic lateral sclerosis (ALS) is a neurodegenerative disease characterized by progressive muscular paralysis reflecting degeneration of motor neurons in the primary motor cortex, corticospinal tracts, brainstem and spinal cord. "Additionally, DYNC1H1 may be related to amyotrophic lateral sclerosis (ALS)." (PMID 36882741, 2023).
breast carcinoma (2 papers, 2021 to 2023).
cataract (2 papers, 2016 to 2025). Partial or complete opacity of the crystalline lens of one or both eyes that decreases visual acuity and eventually results in blindness. "As DYNC1H1 is expressed in the elongating fiber cells of the lens and possibly traffics vesicles along microtubules for reorganization of the fiber cell, it is possible that mutations in the motor domain disrupt the development of the lens and result in cataracts." (PMID 27754416, 2016). "Mutations in the DYNC1H1 gene, encoding a protein with functions and a structure very similar to those of DNAH9, cause cataracts." (PMID 40649110, 2025).
congenital hydrocephalus (2 papers, 2024 to 2026). Hydrocephalus that is present at birth. "In this manner, by clarifying how Dnah5 and Dync1h1 contribute to the causes and progression of congenital hydrocephalus, this research holds promise for identifying novel therapeutic targets, developing early diagnostic tools, and building a foundation for more effective personalized medicine." (PMID 39594631, 2024).
focal epilepsy (2 papers, 2022 to 2023). A seizure caused by a localized disorder. "Herein, we report a case of drug-resistant focal epilepsy associated with a pathogenic variant of DYNC1H1." (PMID 36636459, 2022).
frontotemporal dementia (2 papers, 2021 to 2023). Frontotemporal dementia (FTD) comprises a group of neurodegenerative disorders, characterized by progressive changes in behavior, executive dysfunction and language impairment, as a result of degeneration of the medial prefrontal and frontoinsular cortices. "The DHTKD1 gene causes not only ALS, but also CMT2 and SMA, and ALS-frontotemporal dementia may be associated with DYNC1H1 mutation." (PMID 36882741, 2023).
glioblastoma (2 papers, 2021 to 2022). The most malignant astrocytic tumor (WHO grade IV). "Somatic mutations of DYNC1H1 have been detected in several cancers, including intraductal papillary mucinous neoplasm, pancreatic neuroendocrine neoplasm, and glioblastoma multiforme." (PMID 34272765, 2021).
glioma (2 papers, 2022 to 2023). A benign or malignant brain and spinal cord tumor that arises from glial cells (astrocytes, oligodendrocytes, ependymal cells). "The volcanic plot showed the differential analysis results of these six RBP genes, which showed that POLR2F and DYNC1H1 were downregulated in glioma, while TRIM21, BRCA1, ERI1, and SMAD9 were upregulated in glioma." (PMID 36118697, 2022). "Lin established a 6-RBP gene signature consisting of POLR2F, DYNC1H1, SMAD9, TRIM21, BRCA1, and ERI1 in another bioinformatics work, allowing for a complete assessment of glioma and ischemic stroke." (PMID 37884559, 2023). "In all WHO grade II-IV gliomas, DNAss was positively correlated with the RBPS score, ERI1, BRCA1, and TRIM21, while negatively correlated with POLR2F, DYNC1H1, and SMAD9 [Spearman correlation, Benjamini-Hochberg (BH)-adjusted p < 0.05]." (PMID 36118697, 2022). "First, six prognostic-related RBP genes (POLR2F, DYNC1H1, SMAD9, TRIM21, BRCA1, and ERI1) were obtained from the TCGA-glioma dataset." (PMID 36118697, 2022). "Among them, POLR2F, DYNC1H1, and SMAD9 in tumor tissues of patients with glioma were downregulated as compared to normal tissues adjacent to cancer, while TRIM21, BRCA1, and ERI1 were upregulated." (PMID 36118697, 2022).
Huntington disease (2 papers, 2012 to 2020). Huntington disease (HD) is a rare neurodegenerative disorder of the central nervous system characterized by unwanted choreatic movements, behavioral and psychiatric disturbances and dementia. "Some altered proteins are even more specifically linked to pathology of Huntington's disease, such as Heat shock protein-70 (Hspa1b), cytoplasmic dynein 1 heavy chain 1 (Dync1h1)." (PMID 23094041, 2012).
lung carcinoma (2 papers, 2022 to 2025). "High DYNC1H1 expression in lung cancer tissues was significantly associated with clinical tumor stage, distal metastasis, and poor prognosis." (PMID 40798857, 2025). "Although DYNC1H1-associated immune responses have been identified among various types of cancer, comprising gastric and lung cancer, the role of DYNC1H1 in immune infiltration and prognosis is still underexplored." (PMID 35601740, 2022).
neuropathy (2 papers, 2018 to 2021). A disorder affecting the nervous system that manifests with pain, tingling, numbness, and/or muscle weakness. "To gain understanding of the onset and progression of axonal CMT as well as the role of cytoplasmic dynein in cellular neuropathy, we have generated and initially characterized a knock-in mouse carrying the H304R mutation in the Dync1h1 cytoplasmic dynein heavy chain gene." (PMID 29379136, 2018).
ovarian carcinoma (2 papers, 2023). A malignant neoplasm originating from the surface ovarian epithelium. "Analysis of pathological stage indicated differential expression levels of GPR137 and DYNC1H1 across varying stages of ovarian cancer." (PMID 38021163, 2023). "Bioinformatics prediction unveiled a close association of GPR137, NDEL1, DYNC1H1, and TUBA1A with ovarian cancer development and prognosis." (PMID 38021163, 2023). "Further, multiple gene correlation analyses revealed a significant positive linear relationship between GPR137 expression in ovarian cancer tissues and the expression levels of NDEL1, DYNC1H1, and TUBA1A." (PMID 38021163, 2023). "Moreover, by examining clinical data, we found that the expression of four genes, GPR137, NDEL1, DYNC1H1, and TUBA1A, differed significantly between tumor tissues and normal tissues, and their expression levels were significantly associated with poor prognosis of ovarian cancer patients." (PMID 38021163, 2023). "Thus, the findings of the analysis indicate a significant correlation of the expression levels of GPR137, NDEL1, DYNC1H1, and TUBA1A with the advancement and prognosis of ovarian cancer." (PMID 38021163, 2023).
Parkinson disease (2 papers, 2021 to 2023). A progressive degenerative disorder of the central nervous system characterized by loss of dopamine producing neurons in the substantia nigra and the presence of Lewy bodies in the substantia nigra and locus coeruleus. "Suspecting atypical Parkinsonism, a Wilson disease study and genetic tests of Charcot–Marie–Tooth (CMT), atypical Parkinsonisms (PARKs, GAB, DNAJC6, VPS13C, PINK, and LG), and atypical spinal–muscular atrophies (DYNC1H1, BICD, VAPB, GARS, DYNC1H1, mtATP6, and mtATP8) were carried out." (PMID 37510225, 2023).
–muscular atrophies (2 papers, 2020 to 2023). "A hypothesis why the muscular atrophy in DYNC1H1–NMD affects predominantly the lower extremities is that neuronal transportation distance is longer compared with the upper extremity or the cortex, thus being more sensitive by a deduction in run length." (PMID 32788638, 2020).
Anxiety (1 paper, 2021). Intense feelings of nervousness, tension, or panic often arise in response to interpersonal stresses. "Therefore, we sought to probe whether DYNC1H1 gene polymorphisms have an effect on mental disorders (anxiety and depression) and HRQOL in SLE patients." (PMID 34272765, 2021). "Our study intends to investigate whether DYNC1H1 gene SNP/CNV is related to SLE susceptibility, GCs efficacy, HRQOL, anxiety, and depression in Chinese SLE patients." (PMID 34272765, 2021). "Nevertheless, the effect of DYNC1H1 gene polymorphism on GCs efficacy and mental disorders (anxiety and depression) was not discovered." (PMID 34272765, 2021). "In addition, logistic regressions were used to analyze whether DYNC1H1 gene has an effect on anxiety, depression, and HRQOL in 453 baseline patients." (PMID 34272765, 2021). "No one has yet considered linking the variations in DYNC1H1 with anxiety and depression." (PMID 34272765, 2021).
Atonic seizure (1 paper, 2021). Atonic seizure is a type of motor seizure characterized by a sudden loss or diminution of muscle tone without apparent preceding myoclonic or tonic event lasting about 1 to 2 seconds, involving head, trunk, jaw, or limb musculature. "Besides IS, several epileptic phenotypes have been reported in patients with DYNC1H1 variants, such as focal onset epilepsy, myoclonic epilepsy, and atonic seizures." (PMID 34803881, 2021).
Atrophy (1 paper, 2016). Any weakening or degeneration, especially through lack of use. "The phenotype (foot deformity at birth, delayed motor milestones and lower limb weakness and atrophy) matched the DYNC1H1’s disease association with reasonable specificity." (PMID 26846447, 2016).
autosomal dominant congenital cataracts (1 paper, 2023). "Variants in DYNC1H1 have been associated previously with autosomal dominant congenital cataracts." (PMID 36980880, 2023).
autosomal dominant lower extremity-predominant spinal muscular atrophy 1 (1 paper, 2020). "Mutations in the cytoplasmic dynein 1 heavy chain 1 gene (DYNC1H1) were first described in 2010 in autosomal dominant lower extremity-predominant spinal muscular atrophy 1 (SMALED1; MIM#158600)." (PMID 32788638, 2020).
ciliopathies (1 paper, 2025). "The study found that SPAG6, TRAF3IP1, IFT22, and KIF3B showed lower correlations with ciliopathies, while IFT172, TTC21B, CEP290, ACTB, and DYNC1H1 were highly correlated." (PMID 40432967, 2025).
colon adenocarcinoma (1 paper, 2016). "We have identified DYNC1H1,GRIN2A, and GRM1 as novel hub driver genes for the stage-II progression of colon adenocarcinoma." (PMID 27243824, 2016).
congenital cataracts (1 paper, 2016). "The patient’s symptoms are consistent with a variety of the phenotypes observed in other patients and mice with mutations in DYNC1H1 with the notable addition of congenital cataracts and gut dysmotility." (PMID 27754416, 2016).
COVID-19 (1 paper, 2021). A disease caused by infection with severe acute respiratory syndrome coronavirus 2. "GSEA of the COVID-19-related gene sets indicated that three genes namely DYNC1H1, LMNA, and DCTN1 were downregulated in human bronchial epithelial cells in COVID-19 after 24hr of infection (GSE17400)." (PMID 34832615, 2021).
development (1 paper, 2017). "In a previous study, frequent recurrence of mutations in DYNC1H1 (8 different de novo mutations in 16 unrelated probands) was described in a cohort of individuals affected by the malformations of cortical development (MCD) disorder using WES29." (PMID 28325891, 2017).
distal arthrogryposis (1 paper, 2018). A muscle tissue disease characterized by congenital joint contractures of hand and feet. "Expression of several genes linked to motor neuronopathy and familiar amyotrophic lateral sclerosis (EPHA4, IGHMBP2, VAPB, BICD2, and DYNC1H1) or distal arthrogryposis (MYH8, ZC4H2, MUSK, RAPSN) were significantly upregulated or downregulated." (PMID 29727687, 2018).
gastric tumor (1 paper, 2023). "Among autophagy genes in the Reactome database, PRMT1 was negatively correlated with genes such as ATG9A, DYNC1H1, EPAS1, PINK1, TSC1, TUBB6, and ULK1 in gastric tumor tissues (STAD-TCGA) and positively correlated with HMMR, ESCO2, CHAC2, and NUDT6 (STAD-TCGA)." (PMID 37564212, 2023).
hereditary hemorrhagic telangiectasia (1 paper, 2026). A disorder of angiogenesis leading to arteriovenous dilatations: cutaneo-mucosal hemorrhagic telangiectasias and visceral shunting. "Dominant causes included 22q deletion syndrome, DYNC1H1, SCN3A, and hereditary hemorrhagic telangiectasia (HHT) genes, ACVRL1 and ENG." (PMID 41670011, 2026).
Hydrocephalus (1 paper, 2024). Hydrocephalus is an active distension of the ventricular system of the brain resulting from inadequate passage of CSF from its point of production within the cerebral ventricles to its point of absorption into the systemic circulation. "Our research indicates that Dnah5 deficiency-induced downregulation of Dync1h1 is involved in cortical development abnormalities and hydrocephalus progression." (PMID 39594631, 2024).
lupus (1 paper, 2021). "DYNC1H1 is located on chromosome 14q32.31, which has a miRNA cluster that regulates 48 lupus susceptibility genes." (PMID 34272765, 2021).
motor neuron degeneration (1 paper, 2026). "Analysis of bulk RNA-sequencing data from an additional cohort identified deleterious somatic variants in DYNC1H1 and LMNA, genes associated with pediatric motor neuron degeneration." (PMID 41986690, 2026).
Neurodevelopmental delay (1 paper, 2022). "DYNC1H1 variants are associated with peripheral neuronal dysfunction and brain morphology abnormalities resulting in neurodevelopmental delay." (PMID 36636459, 2022).
osteosarcoma (1 paper, 2023). A usually aggressive malignant bone-forming mesenchymal neoplasm, predominantly affecting adolescents and young adults. "These RBPs include NOP58, FAM120C, DYNC1H1, TRAP1, and LMNA, which may serve as molecular targets for osteosarcoma immune regulation." (PMID 37139238, 2023).
retinal degeneration (1 paper, 2021). Degeneration of the retina. "We previously reported that conditional knockout of Dync1h1 in mouse retina (Dync1h1F/F;Six3cre or retDync1h1−/−) resulted in rapid retinal degeneration within 2 postnatal weeks." (PMID 34807236, 2021).
uterine corpus endometrial carcinoma (1 paper, 2020). A endometrial carcinoma (disease) that involves the body of uterus. "Moreover, DYNC1H1 was highly mutated in Uterine Corpus Endometrial Carcinoma (UCEC) and GC." (PMID 33221769, 2020).